CCL2 (C-C motif chemokine ligand 2)
Diseases named in the same sentence as CCL2 in open-access papers (continued):
Sharing a sentence is not in itself a finding about the gene and the disease.
tumor (continued). "Here, the mRNA levels of proinflammatory cytokines Tnfa, Il6, Il1b as well as the chemokine Ccl2 were significantly higher in Plg− tumors relative to Plg+ tumors consistent with the smaller tumor size and increased levels of apoptosis." (PMID 37971174, 2024). "iCAFs are promoted by fibroblast activation protein (FAP) and STAT3 activation, resulting in secretion of CCL2 and IL-6, significant for promoting MDSCs infiltration into the tumour microenvironment and supporting the growth of malignant cells." (PMID 38920685, 2024). "MCP-1 (monocyte chemoattractant or CCL2) targets monocyte migration into the tumor microenvironment, facilitating metastatic seeding by VEGF-A-mediated angiogenesis." (PMID 38397942, 2024). "In order to directly explore the role of CCL2 in the biological behavior of tumor cells, 100 ng/mL of the CCL2 recombinant protein was used to evaluate the proliferation, invasion, and migration abilities of PC-3 and 22RV1 cells." (PMID 38221626, 2024). "Multiple cell types in the TME—endothelial cells, stromal cells, and tumor cells—tend to produce CCL2, which recruits monocytes and TAMs to the tumor sites." (PMID 39125273, 2024). "To address this critical question, we constructed LL2 subcutaneous tumour models of WT, CCL2−/−, and LTB4R−/− mice and treated them with oxPAPC on day 0 after tumour inoculation (10 mg/kg, intraperitoneal injection, once every other day)." (PMID 37905494, 2024). "In detail, CCL2 is recognized for its role in recruiting TAMs to tumor tissues and influencing their polarization, as well as MDSC." (PMID 38952044, 2024). "Their migration into metastatic tumor colonies required signaling between CCL2 and CCR2, and their antitumor effects required CCL6-dependent recruitment of NK cells." (PMID 39545417, 2024). "Monocytes are recruited to the tumor microenvironment via the CCR2/CCL2 axis, which has emerged as a potential target in approaches to slow cancer progression." (PMID 39545417, 2024). "Within the local tumor microenvironment, the expression of PD-L1 and CCL2 is increased, with PD-L1 facilitating RANKL-induced osteoclastogenesis through JNK activation and CCL2 release." (PMID 39148909, 2024). "Overall, these findings suggest that malignant BCa cells with increased HSP47 expression increase the expression of various pro-angiogenic factors, including CCL2, which then increases angiogenesis, migration, and tumor burden." (PMID 39409924, 2024). "This was because local CNN4 expression inhibited the release of IFN from CD8 + T cells and increased tumor secretion of MDSCs-attracting chemokines such as CCL2 and CXCL1." (PMID 38609997, 2024). "In the current literature, the blockade of either CCL2 or CCR4 was reported to have additional anti-tumor influence by targeting different than Treg subsets of pro-tumorigenic cells in various cancers." (PMID 39046599, 2024). "Several different cell types, such as tumor cells and endothelial cells, secrete CCL2, which binds to the CCR2 receptor on monocytes, thereby promoting recruitment of monocytes and their differentiation into macrophages." (PMID 38473300, 2024). "Recently, a study identified a novel histone deacetylase 5 (HDAC5)-CCL2/CCR2-TGF-β/SMAD4 axis driven by epigenetic regulation to promote tumor growth in a PDAC model." (PMID 38167055, 2024). "Mechanistically, HDAC5 in tumor cells inhibits Socs3, a negative regulator of CCL2, resulting in a shift from neutrophils to CCR2-expressing macrophages." (PMID 38167055, 2024). "Animal model research has revealed that anthracycline drugs can elevate the levels of CCL2 in the tumor microenvironment, thereby attracting antigen-presenting cells and facilitating robust immune responses against the tumor." (PMID 39420203, 2024). "Patients with lower levels of CCL2+ or CCL17+ cells in their tumours have shown longer survival times compared to those with higher numbers of these cells." (PMID 39031979, 2024).
tumor (continued). "We previously demonstrated that Schwann cells secrete the chemokine CCL2 to promote the invasion of tumor cells along neurites." (PMID 39214988, 2024). "Application of the HIF‐1A blocker or miR‐210‐3p inhibitor showed a notable suppression of tumor cell growth in 3D spheroids along with the induction of CCL2 expression, monocyte migration, and switching macrophage polarity." (PMID 35658112, 2024). "Consistent with cytokine profiling, real-time PCR data confirmed upregulation in the expression of IL8, Cxcl10, Il1β, and Ccl2 in tumor lysates." (PMID 39768223, 2024). "The chemotactic cytokine ligan 2 (CCL2)-chemokine (C-C motif) receptor 2 (CCR2) axis activates tumor cell metastasis and regulates the recruitment and polarization of immune cells, affecting cancer progression and recurrence." (PMID 39138521, 2024). "In order to recruit macrophages into the TME, tumor cells secrete various chemokines, including CSF-1, CCL2, CCL5, CX3CL1, and CXCL12." (PMID 38341519, 2024). "These signals can promote either a pro-tumor M2 phenotype (e.g., IL-4, IL-10, TGF-beta, and CCL2) or can drive TAMs towards an anti-tumor M1 phenotype (e.g., IFN-gamma and TNF-alpha)." (PMID 38730679, 2024). "The results demonstrated a significantly higher proportion of CCL2-positive areas in TLS regions compared to the adjacent tumor tissue." (PMID 39595209, 2024). "It is mainly taken up by monocytes and macrophages, and induces CCL2 up-regulation of macrophages to stimulate strong tumor immune response;CAR-T cell therapy is a new breakthrough in cancer therapy." (PMID 39737395, 2024). "In conclusion, PRPS2 regulated the chemotaxis of TAM and MDSC in tumor cells by controlling CCL2 expression." (PMID 38952044, 2024). "IFN-β, a downstream signal of the cGAS-STING signaling pathway, can also stimulate tumor cells to produce CCL2 and CCL7 and affect the recruitment of M-MDSC." (PMID 39464890, 2024). "Currently, synthetic inhibitors of CCL2, Bindarit(Bnd) and Carlumab(CNTO 888), as well as CCR2 antagonists RS-50439 and MLN1202, have been developed for targeted disruption of CCL2/CCR2 signaling to intervene in the progression of various tumor types." (PMID 38650924, 2024). "CCL2 siRNA treatment of 4T1 tumor-bearing mice increased myofiber size as indicated by measurements of cross-sectional area and Feret diameter, increased MYL expression, and reduced expression of total MYH but not MYH4." (PMID 38973385, 2024). "Activation of TLRs in NSCLC cells leads to upregulation of pro-inflammatory cytokines and chemokines (TNF-α or CCL2), contributing to the immunosuppressive nature of the tumor microenvironment." (PMID 38792335, 2024). "M-MDSCs are rapidly recruited to the inflammatory tumor tissues upon exposure to chemokines such as CCL2, CCL5, CXCL8, and CXCL12 and produce multiple immunosuppressive cytokines such as ARG1, nitric oxide (NO), TGF-β, and IL-10." (PMID 38520006, 2024). "Abundant evidence has confirmed that overexpression of CCL2 boosts tumor metastasis and invasion and induces immune resistance." (PMID 38970074, 2024). "TPV/∆66R/m-CCL-2/mCherry reached statistically greater mean tumor volume, with p < 0.05, compared to control at approximately 30 days post virotherapy." (PMID 39200298, 2024). "The collected evidence highlights that ZBTB18 impairs the recruitment of GAMs to the tumor site by repressing the expression of cytokines with chemoattractant properties, CCL2 in particular." (PMID 39516530, 2024). "Immunohistochemical staining revealed that AAE intervention significantly decreased the proliferative capacity of tumor cells and increased the expression of multiple chemokines, including CCL2, CCL5, and CCL10." (PMID 39206194, 2024). "For example, in lung squamous cell carcinoma, CCR2 + monocytes are induced to migrate toward the tumor site by CAFs-secreted CCL2 and are then reprogrammed to M-MDSCs." (PMID 38609997, 2024).
tumor (continued). "Despite the described factors, the influence of CCL2 on the tumor environment should also be mentioned." (PMID 39199602, 2024). "We established LL2 tumour‐bearing models in WT, CCL2−/− and LTB4R−/− mice, and treated them with oxPAPC." (PMID 37905494, 2024). "Immune modules also captured highly correlated inter-tissue/inter-omic features, such as granulysin (gnly) mRNA expression in tumor biopsy samples and serum CCL2 protein, which were higher in responders." (PMID 38670099, 2024). "At the same time, Wnt5a also triggered Ca2+/CaKMII pathway in M2 and increasing CCL2 paracrine secretion, knockdown of β‐catenin in M2 inhibited TAMs' tumor‐promoting activities." (PMID 38349050, 2024). "In solid tumors, including TCC, macrophages are attracted to the tumor site through chemotactic molecules such as CCL2 (MCP-1) and CSF-1 (M-CSF)." (PMID 38338162, 2024). "Consistent with this, our in vivo experiments proved that oxPAPC triggered macrophages secreting MCP‐1 and LTB‐4, which recruited monocytes and neutrophils into tumour respectively through the MCP‐1/CCL2 and LTB‐4/LTB4R axis." (PMID 37905494, 2024). "Previous studies demonstrated that growth factors and chemokines secreted by TAMs, such as PDGF-A, VEGF-A, and CCL2, increase tumor cell proliferation." (PMID 38689086, 2024). "Monocytes are recruited to the tumor site through CCL2/CCR2, inhibiting CD8+ T cell infiltration and recruiting regulatory T cells (Tregs)." (PMID 39253716, 2024). "By interacting with CCR2, CCL2 facilitates cancer cell migration and recruits immunosuppressive cells to the tumor microenvironment, thereby promoting cancer development." (PMID 38533503, 2024). "In contrast, nitrated CCL2 has an unaltered ability to recruit MDSCs into the tumor core, while accumulation and induction of MDSCs is further promoted by iNOS-dependent upregulation of vascular endothelial growth factor (VEGF) secretion." (PMID 39211039, 2024). "Antibody-mediated CCL2 blockade inhibited monocyte recruitment to primary breast tumors, which led to tumor growth suppression and improved patient survival." (PMID 39003350, 2024). "LNMAT1 is upregulated in bladder cancer, which stimulates lymphangiogenesis and metastases by epigenetically activating CCL2 expression recruiting TAMs into the tumor beds, and facilitating lymphatic metastasis through the excretion of VEGF‐C137." (PMID 38703051, 2024). "The chemokines that are highly expressed in the TME of glioblastoma have been characterized by CXCL2, IL-8, and CCL2, which can promote tumor invasion via facilitating cell proliferation, tumor growth, and angiogenesis." (PMID 39061427, 2024). "TAMs-derived IL-1β stimulates GBM tumor cells and induces the expression of IL-1β itself and CCL2, which actively recruits TAMs in the tumor site." (PMID 38397187, 2024). "After the biopsy, tumor tissue induces migration and proliferation of tumor cells by the recruitment of CCL-2-dependent macrophages and increases migrating motor tumor cells." (PMID 38578317, 2024). "When the ER stress signaling pathway is activated, it leads to the secretion of immune-suppressive and metastasis-related cytokines, such as CCL2, by tumor cells, reshaping the tumor microenvironment for immune cell evasion." (PMID 39280014, 2024). "Because the chemokine CCL2 regulates myeloid cell recruitment and low CCL2 expression was found in miR-126 OE tumor tissues, we examine the number of CD11b and F4/80 expressing myeloid cells in tumors." (PMID 39419989, 2024). "Compared to BM-MSCs, TA-MSCs exhibit significantly elevated levels of CCL2 and can recruit TAMs to enhance primary tumor growth, invasiveness, and metastatic speed." (PMID 38779660, 2024). "IL6R and CCL2 exhibited elevated expression in NK cells in HPV − tumor tissues compared with HPV + tumor tissues." (PMID 38468260, 2024). "CAFs also secrete chemokines like CCL2 that recruit endothelial progenitor cells (EPCs) to the tumor site, contributing to neovascularization." (PMID 39519109, 2024).
tumor (continued). "To elucidate the factors governing G-MDSC recruitment in CRNDE-induced HCC, we examined putative G-MDSC-recruiting chemokines, indicating that the expression of Cxcl3, Cxcl1, Cxcl5, and Ccl2 was significantly increased in upregulated Crnde tumor cells." (PMID 38169579, 2024). "Our results showed that RUNX1 derived from tumor cells recruits TAMs cells and induces macrophage polarization into the M2 state by promoting the secretion of CCL2 and the activation of Hedgehog signaling pathway." (PMID 38419056, 2024). "Blocking EZH2 in orthotopic, murine, KPC tumors, treated with MEK and CDK4/6 inhibitors, subsequently led to an increase in intra-tumoral CCL2 and CXCL9/10 production and was associated with NK- and T-cell influx and anti-tumor responses." (PMID 38339310, 2024). "In tumor cells, we observed activation of genes associated with cell proliferation (TMSB10, IGFBP3), migration (CCL2), signal transduction (DUSP1), and other behaviors." (PMID 38191424, 2024). "In tumor cells, mitochondrial fission mediated by DRP1 enhances the recruitment of TAMs by releasing mtDNA, which promotes the release of the chemokine CCL2, thus facilitating tumor progression." (PMID 38812059, 2024). "CCL2+ or CCL17+ tumor-associated neutrophils (TANs) were observed in the stroma of HCC, and conditioned media from TANs or recombinant CCL2 or CCL17 increased migration of macrophages and regulator T cells (Tregs)." (PMID 39682130, 2024). "GBM cells induce macrophages to infiltrate the tumor microenvironment by upregulating CCL2 and CCL7, and then macrophages promote tumor growth and survival by delivering LDHA to tumor cells." (PMID 39493751, 2024). "MPE tumor-secreted CCL2 not only acts in an autocrine fashion to promote EMT and trans-endothelial migration, but also recruits tumor associated macrophages and drives M2 polarization." (PMID 39114667, 2024). "Tumor‐derived CCL2 is a potent monocyte‐chemotactic protein and its high level correlates with increased numbers of TAMs in tumor tissues." (PMID 35658112, 2024). "CAFs can regulate tumor microenvironment by releasing cytokines (IL-6) and chemokines (CCL2 and CXCL10)." (PMID 38896161, 2024). "Specifically, CAFs have been implicated in the recruitment and transendothelial migration of monocytes from circulating vasculature to tumor sites through the secretion of chemokines (including CCL2) and induction of chemotactic gradients." (PMID 39700125, 2024). "CCL2 is a C-C chemokine ligand produced mainly by activated T cells and plays an important role in tumor progression by activating the host pro-tumor phenotype after binding to the classical CCR2." (PMID 39350256, 2024). "By immunostaining, 4T1 tumor-bearing mice showed increased CCL2 expression in tumors, corresponding to CCL2 levels in skeletal muscle tissue." (PMID 38973385, 2024). "One of the primary mechanisms by which CCL2 promotes tumor progression involves its interaction with MDSCs." (PMID 39456702, 2024). "The binding of programmed death-protein 1 (PD-1) on the T cell surface and its co-inhibitory ligand (CCL2) on the tumor surface results in T cell exhaustion and promotes tumor survival." (PMID 39544364, 2024). "CCL2 attracts immunosuppressive cells to the tumor microenvironment, thereby favoring cancer development." (PMID 38160212, 2024). "Our findings conclusively showed that the increased infiltration of Ly6Chigh monocytes and neutrophils into tumour tissues elicited by oxPAPC treatment in vivo is mediated by MCP‐1/CCL2 and LTB4/LTB4R signalling pathways." (PMID 37905494, 2024). "It has been proposed for a considerable time that TAMs originated from circulating monocytes, and are attracted to tumors through chemotactic signals emitted by the tumor, such as C-C motif chemokine ligand 2, CCL2)." (PMID 39065562, 2024). "The CCL2/CCR2 axis plays multiple protumorigenic roles and is implicated in cancer formation and metastasis, tumor cell invasion and the promotion of angiogenesis." (PMID 39457710, 2024).
tumor (continued). "For example, bevacizumab (an anti-VEGF therapy) combined with the CCL2 inhibitor mNOX-E36 decreased the recruitment of TAMs and angiogenesis, resulting in decreased tumor volume in a rat glioblastoma multiforme model." (PMID 39516356, 2024). "Especially if the RFA treatment was incompletely conducted, heat stress induces cancer stemness or production of immune suppressive chemokines such as CCL2, resulting in tumor progression and reduction in the effectiveness of immune checkpoint inhibitors." (PMID 39559295, 2024). "Downregulated c-MYC expression is consistent with tumor growth suppression on blocking of the CCL2/CCR2 axis, which is a potential target for patients with hepatocellular carcinoma and chronic hepatic inflammation." (PMID 37450923, 2024). "Dimethyl itaconate decreases CCL2 production in epithelial cells, reduces macrophage recruitment to the tumor microenvironment, alleviates the hyperinflammatory state of UC, and lowers the risk of colitis-associated cancer." (PMID 39850880, 2024). "CCL2 released by SCs enhances the proliferation, migration, and invasion capabilities and EMTs of tumor cells, as well as induces TAMs to polarize into the M2 subtype, resulting in immunosuppression." (PMID 38334648, 2024). "Stromal factors, such as CCL2, IL-6, and TGF-β1, produced by tumor-associated stromal myofibroblasts induce an immunosuppressive phenotype by increasing the expression of CD209 and PD-L1." (PMID 39459945, 2024). "SNAIL expression in tumor cells increases their secretion of CCL2, CCL5, and CXCL2, all of which attract macrophages to the TME." (PMID 39555068, 2024). "Compared with that in the supernatant from WT tumor cells, the level of secreted CCL2 in the supernatant from Ifi35ko 4T1 or EMT6 tumor cells was significantly reduced." (PMID 38216673, 2024). "Studies have revealed that the IL-17A/IL-17RA signaling pathway is activated in oral cancer cells infected with Candida albicans, which induces CCL2 and attracts macrophages into the tumor environment." (PMID 39906741, 2024). "The tumor group exhibited a higher CCL2 expression level than that in the normal group, indicating a median difference of 2.653 between the two groups (2.478–2.829, p < 0.001)." (PMID 39030882, 2024). "Our study also provided evidence that the IL6/IL6R and CCL2/CCR2 signaling pathways within the TME exert a greater influence on the ability of HPV − tumor cells to evade immune attack by NK cells compared to HPV + tumors." (PMID 38468260, 2024). "CCL2, another chemokine arising from M2 TAMs, promotes tumor growth, metastasis, and EMT processes by inhibiting autophagy." (PMID 39169402, 2024). "The combination of bevacizumab with an anti-CCL2 antibody has shown a synergistic effect in inhibiting tumor growth and angiogenesis." (PMID 38844562, 2024). "In a positive feedback loop, tumor cells treated with M2 macrophage-derived exosomes express higher levels of CCL2, leading to increased macrophage recruitment and M2 polarization." (PMID 39555068, 2024). "Among the most prominently expressed chemokine genes in GBM tissue, CCL2 is the chemokine gene that was expressed by myeloid cells, tumor cells, and pericytes." (PMID 39272976, 2024). "Inhibitors targeting the CCL2/CCR2 or CSF-1/CSF-1R signaling axis have shown promise in reducing macrophage accumulation at tumor sites." (PMID 39146202, 2024). "Anti-CCL2 therapy has been proposed to be a potential strategy to enhance NK cell activity, leading to more effective anti-tumor responses." (PMID 38160212, 2024). "CCL2 was responsible for tumor recruitment of CCR2+ MDSCs and CCR4+ Tregs, suggesting the critical role of CCL2 in the generation of an immunosuppressive TME." (PMID 38786066, 2024). "This response was guided by macrophages and Natural Killer (NK) cells migrated into the tumor bed following the release of CCL2 (previously called MCP1), CXCL1, and IL-15." (PMID 38561826, 2024).